METTL3 (methyltransferase 3, N6-adenosine-methyltransferase complex catalytic subunit)
Diseases named in the same sentence as METTL3 in open-access papers (continued):
Sharing a sentence is not in itself a finding about the gene and the disease.
tumor (continued). "PDGF triggers mRNA decay of the tumor suppressor OPTN via METTL3, thereby suppressing mitophagy and targeting of METTL3 reduced tumor growth in GSC derived PDX models." (PMID 37444568, 2023). "We found that METTL3 knockout efficiently delayed tumor growth, as the weights and sizes of METTL3-deficient xenografts displayed a significant decrease compared with the compared group." (PMID 38001065, 2023). "We also analysed DCP2 expression in subcutaneously transplanted nude mouse tumours in which we knocked down or overexpressed METTL3." (PMID 36932427, 2023). "In vivo experiments also demonstrated that treatment with the METTL3 inhibitor significantly suppressed tumor growth." (PMID 38012755, 2023). "In response, M2-TAMs significantly enhance METTL3 expression in lung adenocarcinoma cells, leading to increased m6A methylation levels and overall levels of immune resistance, thus promoting tumor progression." (PMID 38187373, 2023). "Mechanistically, METTL3 impedes tumor progression through m6A modification on NF-κB mRNA in a YTHDF2-dependent manner, which in turn attenuates IL-8 production of papillary TC cells to recruit neutrophils, ultimately suppressing tumor progression." (PMID 37915103, 2023). "Next, we detected METTL3 expression in 13 pairs of pre- and post-chemotherapy HR+HER2− BC tumour tissues and observed that METTL3 expression was deficient in the post-chemotherapy tissues compared to the pre-treatment tissues." (PMID 36765397, 2023). "Overall, while METTL3 appears to actas a tumor suppressor in afew cases, many reports suggest that METTL3 inhibition very likelyhas beneficial effects in numerous cancer types." (PMID 36692498, 2023). "Next, we investigated the role and mechanism of METTL3 in the immune response to EC using a mouse tumor model and a CD8+ T cell-EC cell coculture system after METTL3 overexpression or depletion." (PMID 37085864, 2023). "METTL3 has been found to play a critical role in tumorigenesis, tumor growth, metastasis, metabolic reprogramming, immune cell infiltration, and tumor drug resistance." (PMID 37996892, 2023). "Taken together, these results indicate that upregulation of METTL3 combined with DOX significantly suppresses the tumour growth." (PMID 36765397, 2023). "Patients in the METTL3 high expression group were more likely to present with higher tumor stage (III + IV, P = 0.0020) and distant metastasis (P = 0.0169)." (PMID 37344779, 2023). "Altogether, Mettl3 deletion in myeloid cells increases Cybb expression, forming a tumor-promoting feature of granulocytes during immune response against tumor growth." (PMID 37932814, 2023). "In particular, METTL3 expression is elevated in a variety of tumor, enhancing the m6A levels of different target genes." (PMID 37996892, 2023). "Recently, lactate accumulation, a tumor micorenvironment condition of solid tumors, also directly regulates METTL3 expression, which depends on H3K18 lactylation." (PMID 37015927, 2023). "Alterations in the expression of m6A writers (i.e. METTL3 and METTL14), erasers (i.e. FTO) or readers (i.e. YTHDC2 and YTHDF1), for example, are associated with tumor-suppressive or tumor-promoting scenarios." (PMID 36866275, 2023). "In the current study, we confirmed a consistent rise of METTL3 in 62 previously obtained STAD tumor tissues, but this was relative to paracancerous normal samples." (PMID 37344779, 2023). "For example, METTL3 or METTL14 deficiency in colorectal carcinoma cells increases recruitment of CD8+ T cells and the levels of IFN-γ, CXCL9, and CXCL10 in the tumor microenvironment." (PMID 37485079, 2023). "In the present study, we found that METTL3 knockdown facilitated, while overexpression of METTL3 suppressed the proliferation of VSMCs, which indicated that the role of METTL3 in VSMCs is diametrically opposite to that in tumour cells." (PMID 36564367, 2023).
tumor (continued). "Exploration of the role of METTL3 in tumor glycolysis facilitates the elucidation of the specifics of energy metabolism within tumor cells, which undoubtedly broadens our view of metabolic reprogramming in tumors." (PMID 37996892, 2023). "In summary, the regulation of AKT signaling by METTL3-mediated m6A plays an important role in tumor cell proliferation, but the mechanisms involved remain to be further explored." (PMID 37996892, 2023). "Deletion of METTL3 in myeloid cells creates an environment conducive to tumor growth and metastasis by increasing infiltration of immunosuppressive cells." (PMID 37485079, 2023). "Tumor-intrinsic METTL3 knockin significantly enhanced the expression of crucial pathways for CD8+ T cell dysfunction, such as cholesterol metabolism, ferroptosis, phagosome, and lysosome." (PMID 37586322, 2023). "The downregulated expression of METTL3 is also observed in tumor-infiltrating NKs of HCC patients, supporting the critical role of METTL3 regulating the function of NKs in carcinogenesis." (PMID 37928272, 2023). "METTL3 is a pivotal m6A methyltransferase and has recently been reported to be involved in lncRNA stability in tumor progression." (PMID 37270527, 2023). "In hepatoblastoma, abnormally high expression of METTL3 leads to a significant increase in m6A levels in the tumor, and m6A is enriched not only near the mRNA stop codon but also in the coding sequence (CDS) region." (PMID 36830614, 2023). "In particular, the expression levels of METTL3/14 have been observed to regulate immune function in individuals with GI cancers and impact the effectiveness of tumor immunotherapy." (PMID 38187373, 2023). "Taken together, our results showed that LINC00839, modified by METTL3-mediated m6A, exerts tumor progression and radiation resistance by activating Wnt/β-catenin signaling." (PMID 37438359, 2023). "METTL3 expression was found to be upregulated in various tumor tissues, particularly in TIMs compared to normal adjacent tissues." (PMID 38187373, 2023). "Currently, an increasing number of studies point to METTL3 as a biomarker that has a definite relationship with tumor prognosis, metastasis, diagnosis, and drug resistance." (PMID 38053093, 2023). "Multiple studies have shown that METTL3 exerts tumor-promoting functions in CRC by regulating gene expression in an m6A-dependent mechanism." (PMID 37152066, 2023). "Pharmacologic targeting of METTL3 augmented the anti-tumor efficacy of the PDGF receptor (PDGFR) and mitophagy inhibitors in vitro and in vivo." (PMID 36835633, 2023). "STM2457 is a high-efficiency selective first-in-class catalytic inhibitor specific to METTL3, and using it for tumor treatment can weaken the AML growth, and enhance the cell differentiation and apoptosis." (PMID 38077322, 2023). "Consistent with its protumoral role, METTL3 enhances tumour PD-L1 expression based on previous studies." (PMID 36859310, 2023). "Overall, these results establish a novel function of m6A in modulating NMD and uncover the mechanism by which METTL3 promotes GBM tumor growth and progression." (PMID 36835633, 2023). "Given this intricate and paradoxical relationship, a comprehensive understanding of the role of METTL3/14 in tumor immunity is necessary, with a specific emphasis on deciphering the potential mechanisms of METTL3/14 within the TIME." (PMID 38187373, 2023). "As expected, targeting of METTL3 plus anti-PD-1 exerted the strongest inhibitory effect on tumor growth in vivo, concomitant with the highest level of intratumor IFN-γ+ and GZMB+ CD8+ T cells." (PMID 37586322, 2023). "This review systematically summarizes the factors that regulate METTL3 expression and explores the specific mechanisms by which METTL3 affects multiple tumor biological behaviors." (PMID 37996892, 2023). "circUHRF2 or METTL3 silencing suppressed in vitro cell stemness, migration, and invasion; and in vivo tumor growth and liver metastasis." (PMID 37370759, 2023).
tumor (continued). "Through experimental studies, we observed frequent upregulation of METTL3 in LIHC tumor tissue and cells." (PMID 38012755, 2023). "Xenograft and animal lung metastasis experiments were also conducted to study the functional role of METTL3 or DDX23 on tumor growth and lung metastasis in vivo." (PMID 36977668, 2023). "METTL3 promotes the proliferation, migration, and invasion of TC in vitro as well as tumor growth and lung metastasis in vivo by augmenting miR-222-3p expression and thereby diminishing the expression of serine/threonine stress kinase 4 (STK4)." (PMID 37915103, 2023). "In ovarian cancer, elevated METTL3 was found to contribute to miR‐126‐5p maturation and exert a tumour‐promoting effect." (PMID 36162823, 2023). "METTL3 utilized different miRNAs as a bridge to drive cell proliferation and tumour‐promoting effect in an m6A‐based pattern." (PMID 36162823, 2023). "In recent decades, m6A writers, especially METTL3, have been shown to be abnormally expressed and to play critical roles in the development of a wide range of neoplasms." (PMID 36810108, 2023). "For OSCC, METTL3 immunostaining was observed in both peripheral and central cells of the tumor islands." (PMID 35785826, 2023). "This study showed that Mettl3 is highly upregulated in paracancerous tissues of CC and inhibited tumor cell proliferation and viability." (PMID 37007040, 2023). "Recently, lactate in the tumor microenvironment of CRC has been identified to induce METTL3 expression in tumor-infiltrating myeloid cells via H3K18 lactylation." (PMID 37152066, 2023). "This involves METTL3 reducing the expression of BHLHE41, a transcription factor associated with tumor immunity suppression, by methylating m6A sites on its mRNA." (PMID 38187373, 2023). "In tumor-infiltrating myeloid cells H3K18 lactylation increased N6-adenosine-methyltransferase 70 kDa subunit (Mettl3) expression that modified Jak1 mRNA, thereby strengthening the immunosuppressive functions." (PMID 37584553, 2023). "Given the involvement of the apoptosis signalling pathway in tumour proliferation, western blotting was implemented to visualize changes in the expression of apoptosis-related proteins following METTL3 knockdown or overexpression in MCF-7 and T47D cells." (PMID 36765397, 2023). "TCGA data shows METTL3 expression is significantly higher in tumor tissues than normal tissues in LIHC and METTL3 expression is significantly associated with shorter overall survival in LIHC patients." (PMID 36300630, 2023). "For OSCC, METTL3 immunostaining was presented in both the peripheral and central cells of the tumor islands." (PMID 35785826, 2023). "Deletion of METTL3 led to reduced m6A level and was demonstrated to regulate tumor growth in glioblastoma, cervical cancer, and so on." (PMID 37370759, 2023). "METTL3 knockdown significantly inhibited the growth of the transplanted tumour and significantly reduced the volume of the transplanted tumour following chemotherapy." (PMID 36932427, 2023). "Tumor m6A research has recently gained attention, and the levels of FTO, METTL3, and YTHDC1 were significantly higher in the high-risk group compared to the low-risk group." (PMID 36968601, 2023). "The HE stained of CSCC tissue slides also revealed that compared with the controls, overexpression of METTL3 increased the malignant morphology of the denser tumor, while knockdown of METTL3 reduced the malignant morphology of the looser tumor." (PMID 36710350, 2023). "Our results indicated that tumor-intrinsic METTL3 promotes NAFLD-HCC by attenuating cytotoxic CD8+ T cell response." (PMID 37586322, 2023). "As a result, it is extremely urgent and important to explore the factors that regulate the expression and role of METTL3 in tumor cells." (PMID 37996892, 2023).
tumor (continued). "Surprisingly, the single-cell sequencing data revealed reduced B cell and increased myeloid cell population in tumor-bearing Mettl3-cKO mice than that in WT mice." (PMID 37932814, 2023). "In tumor-infiltrating myeloid cells, histone lactylation enhances the expression of methyltransferase like 3 (METTL3) and promotes the immunosuppressive capacity." (PMID 37945340, 2023). "The expression level of METTL3 mRNA was examined in forty paired tumor specimens and corresponding adjacent normal tissues, and results confirmed the upregulation of METTL3 mRNA level in OS tissues." (PMID 37151889, 2023). "The dot blot assay revealed that CAFs significantly elevated m6A level in tumor tissues; however, METTL3-knockdown abolished this effect." (PMID 37056933, 2023). "In vivo studies using xenograft models further demonstrated the inhibitory effects of STM2457 as well as knocking-down of METTL3 on tumor growth." (PMID 38012755, 2023). "Conversely, METTL3 inhibition or selective knockdown has been proven to reduce the expression of specific targets that are related to tumor angiogenesis, thereby significantly repressing tumor angiogenesis." (PMID 38053093, 2023). "METTL3 reduces tumor cell death through the circCUX1/caspase 1 axis and confers radiation resistance to HPSCC." (PMID 37264402, 2023). "Currently, there exists limited research exploring the mechanisms through which METTL3 regulates B cells within the tumor microenvironment." (PMID 38187373, 2023). "Conversely, a recent study suggested that Mettl3 deficient mice indicated increased M1- and M2-like TAM in B16 and LLC tumor models." (PMID 37932814, 2023). "For macrophages, METTL3 exerts positive control on its polarization and immune functions, ablating METTL3 can promote tumor growth and metastasis." (PMID 36810281, 2023). "For T cells, METTL3 exerts an essential role in regulating the homeostasis and differentiation, influencing the anti-tumor responses in a bidirectional complex manner." (PMID 36810281, 2023). "In breast cancer, the pro-oncogenic function of Mettl3 involves the inhibition of let-7g tumor suppressor translation, which ultimately promotes cancer cell proliferation." (PMID 37007040, 2023). "Our findings establish a potential tumor promotive and chemo-resistant role for METTL3/DDX23 axis in PDAC." (PMID 36977668, 2023). "For instance, METTL3 has been proposed as a tumor-promoting factor, whereas it also plays a role in polarizing M1 macrophages and exhibits anti-tumor effects." (PMID 37737134, 2023). "The data showed that compared with control xenografts, the knockdown of METTL3 slowed tumor growth, whereas the upregulation of METTL3 promoted tumor growth." (PMID 36710350, 2023). "METTL3 plays essential roles in the cell differentiation, reprogramming, embryonic development and tumor progression." (PMID 37958523, 2023). "The downregulation of STEAP2 partially rescued the tumor-suppressive phenotype induced by METTL3 overexpression." (PMID 36835633, 2023). "Recent studies have demonstrated that the METTL3-m6A axis inhibits anti-tumor immunity to support CRC growth." (PMID 37152066, 2023). "For example, METTL3 plays an oncogenic role in most cancer types, but it has also been reported to have tumor-suppressive functions in certain cancer types, such as kidney cancer." (PMID 36300630, 2023). "METTL3, as the core enzyme responsible for m6A methylation, installs m6A on targeted RNAs, thereby influencing alternative splicing in various types of tumour cells." (PMID 37850412, 2023). "Patients with PCa who have high expression of METTL3 exhibited higher rates of tumor recurrence compared to those with low expression of METTL3." (PMID 37915034, 2023). "Taken together, our evidence suggests that tumor-intrinsic METTL3 restricts the activation and effector states of CD8+ T cells to mediate immune escape and NAFLD-HCC progression." (PMID 37586322, 2023).
tumor (continued). "This study compared the ID8 tumor cell growth between WT and myeloid-specific Mettl3 gene knockout mice and revealed enhanced OC cell growth in Mettl3-cKO mice." (PMID 37932814, 2023). "The enhanced tumor growth in Mettl3-cKO mice coincided with accelerated ascites formation presented by a remarkably expanded abdomen and an increased volume of bloody ascites." (PMID 37932814, 2023). "Next, the functional changes of the relatively abundant granulocyte population were analyzed by investigating differentially expressed genes (DEGs) in tumor-bearing Mettl3-cKO and WT mice." (PMID 37932814, 2023). "To this end, we conducted experiments using LIHC cell lines, spheroids, and CDX models to assess the effects of METTL3 inhibition on tumor growth and progression." (PMID 38012755, 2023). "In testicular germ cell tumors (TGCTs), the expression of METTL3 is decreased, which is positively correlated with the tumor infiltration of CD8 + T cells, CD4 + T cells and NK cells." (PMID 36810108, 2023). "It was shown that METTL3 suppressed tumor growth and metastasis and enhanced PD-1 blockade therapy by influencing macrophage reprogramming." (PMID 37151889, 2023). "METTL3 promotes the proliferation, invasion, and migration of OSCC cells in vitro, while METTL3-knockout inhibits tumor growth in vivo." (PMID 36793593, 2023). "On the one hand, depletion of METTL3 facilitates anti-tumor immunity by restraining Treg cells, on the other hand, reduced METTL3 in CD4 + T cell impairs humoral immunity by suppressing the differentiation and functional maturation of T follicular helper cell." (PMID 36810281, 2023). "As a typical reader for m6A methylation, METTL3 and the levels of m6A-modified mRNA are up-regulated in many types of cancer cells and tumor tissues." (PMID 37907575, 2023). "Lactate accumulated potently induced METTL3 upregulation in tumor-infiltrating myeloid cells via H3K18 lactylation." (PMID 37770937, 2023). "METTL3 knockdown in MCF-7/T47D cells decreased the drug sensitivity of HR+HER2− BC cells by promoting tumour proliferation and migration and inhibiting apoptosis." (PMID 36765397, 2023). "Our findings have suggested the potential biological functions of METTL3 in promoting the development of OS, indicating that METTL3 and m6A methylation exert broad influences on tumor progression and precision treatment." (PMID 37151889, 2023). "METTL3, a key component of the N6-methyltransferase complex, has been reported to play an important role in many tumour types." (PMID 36765397, 2023). "The following year, the same team reported that METTL3 inhibited anti-tumor immunity by targeting the m6A-BHLHE41-CXCL1/CXCR2 axis to promote CRC cell proliferation." (PMID 37580808, 2023). "Quantitative PCR analysis showed significantly higher expression of METTL3 in primary liver tumors compared to adjacent non-tumor tissues (n = 16)." (PMID 38012755, 2023). "The JNK/c-jun/METTL3/PD-L1/IGF2BP1 axis contributes to tumour immune escape in an m6A-dependent manner in BC." (PMID 37284313, 2023). "The analysis indicated that, in comparison to the Normal group, the Tumor group's expression of METTL3 was considerably up-regulated, that of FTO was down-regulated, and those of METTL14 and ALKBH5 were not significantly affected." (PMID 37828232, 2023). "Silencing of METTL3 or circUHRF2 effectively delayed tumor growth and resulted in smaller and lighter tumors." (PMID 37370759, 2023). "In orthotopic NAFLD-HCC mouse models, antibody-mediated depletion of CD8+ T cells abolished the effect of METTL3 knockout on tumor growth, implying that the pro-tumorigenic effect of METTL3 largely depends on its inhibitory effect on CD8+ T cells." (PMID 37586322, 2023). "Considering the important role of LATS1 in tumor suppression, we investigated the exact mechanism of METTL3-mediated m6A modification of LATS1." (PMID 36609396, 2023).